TIMP1 (TIMP metallopeptidase inhibitor 1)
Diseases named in the same sentence as TIMP1 in open-access papers (continued):
Sharing a sentence is not in itself a finding about the gene and the disease.
tumor (continued). "We then explored the functional impact of TIMP1 on metastasis in vivo using a nude mouse metastatic tumor models." (PMID 27644693, 2016). "TIMP-1 is an endogenous inhibitor of metalloproteinases, a family of proteins that play a role in tumor invasion and metastases." (PMID 27509063, 2016). "The reduction of tumor volumes was significantly increased for GPI-TIMP-1 treatment compared with soluble TIMP-1 or control treatments." (PMID 27542385, 2016). "Selective TIMP-1 downregulation was also observed in patient tumor samples subsequent to Δ9-THC administration." (PMID 27774065, 2016). "In contrast, TIMP1 was prominently expressed in primary tumor specimens, with strong staining in 26 (27.7 %) samples, weak staining in 24 (25.5 %) samples, and negative staining in 44 (46.8 %) samples." (PMID 27644693, 2016). "Despite some researches have proved that TIMP-1 has a major role as inhibitor of MMPs, its role in tumor invasion and metastasis appears to be more complex." (PMID 27644693, 2016). "For example, up-regulation of HAS2 in breast cancer promotes the invasive potential of tumor cells by suppressing TIMP1." (PMID 27884164, 2016). "We first browse Oncomine and found that the expression level of TIMP1 was significantly high in tumor tissues compared with the related normal mucosae." (PMID 27644693, 2016). "Tumor growth and tumor weight was significantly inhibited in TIMP1-KD injected tumors (p < 0.01), indicating that TIMP1 exert an oncogenic role during colon progression." (PMID 27644693, 2016). "Mice with LLC exhibited a 15% increase in plasma concentration of VEGF (p < 0.01) and a 28% increase in TIMP-1 (p = 0.01) compared to non-tumor-bearing controls." (PMID 27028862, 2016). "A significantly lower rate of tumor growth was observed in mice injected with neutralizing antibodies against TIMP-1 compared with mice injected with the control IgG." (PMID 27130446, 2016). "The TIMP-1 immunoreactivity in the tumor cells was scored, resulting in a total score between 0 and 6 for each biopsy." (PMID 27619981, 2016). "In C6.9 xenografts, Δ9-THC decreased tumor development and tumoral TIMP-1 but had little impact on TIMP-2 or TIMP-3 expression." (PMID 27774065, 2016). "To determine if TIMP-1 is involved in tumor growth in vivo, we used a neutralizing antibody to block TIMP-1 activity in TNBC cells." (PMID 27130446, 2016). "There were statistically significant associations between pre-treatment plasma TIMP-1 and WHO performance status (PS), location of the primary tumor, previous adjuvant chemotherapy, KRAS and BRAF status." (PMID 27509063, 2016). "Higher expression of TIMP-1 is necessary for advancement tumor diameter from pT1a to pT1b, and a process of tumor diameter extension beyond pT1 and pT2a category needs presence of MVI and high nuclear grade." (PMID 27019657, 2016). "TIMP-1 expression was increased in tumor cells compared with benign tissues in 76.6% of the HCC tumors examined." (PMID 25909286, 2015). "In fact, recent studies have revealed that Twist1 contributes to tumor invasion and dissemination by regulating the expression of TIMP1 or MMPs." (PMID 26538215, 2015). "The initial period of tumor growth is enhanced by TIMP-1 expression and this period was followed by tumor necrosis and tumor regression due to TIMP-1 inhibition of an angiogenic response within the developing tumor mass." (PMID 26556867, 2015). "It has been previously shown that IL-12 also regulates the levels of MMP-9 and TIMP-1 in the tumor micro-environment of BC model." (PMID 27275301, 2015). "Senescent cells also secrete factors such as WNT16B, interleukin-6 (IL-6), and tissue inhibitor of metalloproteinases-1 (TIMP-1) that can protect neighboring tumor cells from being killed." (PMID 24981831, 2014). "In situ hybridization of tumor tissues demonstrated that TIMP-1 and TIMP-2 were expressed at elevated levels in the stroma of low Gleason score tumors, but were negative in higher Gleason score tissues (GS 8–10)." (PMID 24978435, 2014).
tumor (continued). "We found that while expression of MMP-2 and MMP-9 was reduced in Spn4A-expressing tumor cells, mRNA expression levels of TIMP-1 and TIMP-2 was significantly increased." (PMID 24961901, 2014). "Mice with LLC exhibited an 11% increase in plasma concentrations of VEGF (p<0.01) and a 47% increase in TIMP-1 (p<0.01) compared to non-tumor-bearing controls." (PMID 25356654, 2014). "The results presented in this study suggested that icotinib suppresses tumor cell invasion by downregulating MMPs and upregulating TIMP-1/2." (PMID 25120710, 2014). "Our previous studies consistently showed that several anti-metastatic food components decrease secretion of TIMP-1 in several tumor cell types." (PMID 25036034, 2014). "TIMPs, which are natural inhibitors of MMPs and contain four members (denoted TIMP-1 to -4), is reported to ameliorate the invasion and metastasis of tumor cells induced by MMPs." (PMID 25171061, 2014). "MMPs, especially MMP-2 and MMP-9, as well as their endogenous inhibitors (TIMPs, especially TIMP1) are known to be important in tumor development, tumor cell invasion and metastasis." (PMID 24959847, 2014). "Previous observations from tumor tissue have indicated that the fraction of TIMP-1 bound in complexes with other molecules is more closely related with a poor prognosis than the fraction of TIMP-1 present as a free molecule." (PMID 24330623, 2013). "Together, these results work against the established dogma and suggest a pro-tumor instead of anti-cancer activity of TIMP-1." (PMID 24143225, 2013). "If the pro-tumor activity of TIMP-1 is MMP-independent and exerted through its indirect promotive effect on CAFs and the TIMP-1 receptor, CD63 expressed by CAFs." (PMID 24143225, 2013). "Earlier studies indicated that TIMPs including TIMP-1 display anti-cancer activities; however, recent studies have demonstrated a paradoxical pro-tumor effect of TIMP-1." (PMID 24143225, 2013). "Data obtained from these co-immunoprecipitation assays using cell lines representing different stages of melanocyte malignant transformation show differential interaction among CD63, Timp1 and β1-integrin along tumor progression." (PMID 23522389, 2013). "TIMP1, an inhibitor of the matrix metalloproteinases (MMPs), has also been shown to promote tumor progression in numerous tissues." (PMID 24279986, 2013). "Our results establish the novel promotive effects of TIMP-1 on cancer progression and on accumulation of CAFs that in turn provides a pro-tumor microenvironment." (PMID 24143225, 2013). "Several studies pointed TIMP1 as a promising tumor biomarker, since it has been found in high levels in the plasma of patients bearing different types of cancer." (PMID 23522389, 2013). "As metastasis accounts for 90% of solid tumor dependent deaths (Gupta and Massagué, 2006), the induction of the metastatic potential of tumor cells by TIMP-1 and HIF-1 must be considered crucial for successful treatment of malignant tumors." (PMID 22807917, 2012). "Because fibroblasts are primary components of tumor stroma and have been shown to secrete pro-tumorigenic factors within the tumor microenvironment, we examined the effect of NO on TIMP-1 protein in the media of fibroblasts." (PMID 22957045, 2012). "In support of these observations, TIMP-1 was found to reduce tumor cell sensitivity to chemotherapeutic drug treatment of cells grown in culture." (PMID 22957045, 2012). "Our results regarding the differences in blood levels of CRP, sCD26 and TIMP-1 among CRC patients vs neoplasm-free participants are in line with those of several previous studies." (PMID 22454079, 2012). "A clue of the role of TIMP-1 in metastatic progression was recently shown utilizing a TIMP-1 knock down in tumor cells which significantly decreased tumor cell invasiveness and reduced the number of metastasis." (PMID 22807917, 2012). "Overexpression of TIMP-1 has been observed to inhibit some tumor growth and suppress metastatic ability of cancer cells." (PMID 22415590, 2012).
tumor (continued). "We summarize evidence for and propose a new context between one of the most central regulators of the proteolytic network, TIMP-1, the major regulator of tumor cell stress response, HIF-1, and its main downstream microRNA (miRNA) effector, miR-210." (PMID 22807917, 2012). "Over-expression of TIMP-1 led to a significant reduction of tumor burden, as compared to the wild type and the scrambled shRNA control groups." (PMID 22230683, 2012). "C-reactive protein, sCD26 and TIMP-1 levels were found to be different in CRC patients compared with participants free of neoplasms." (PMID 22454079, 2012). "Its expression in tumor cells or tissues is associated with MMP9 and with another matrix metalloproteinase, TIMP1." (PMID 22570691, 2012). "In concordance with the earlier results, TIMP-1 over-expression in tumor cells led to a dramatic reduction of tumor growth as well." (PMID 22230683, 2012). "Recently, high level of metalloproteinase inhibitor TIMP-1 in the tumor microenvironment was discovered as a new inducer of HIF-1 in a liver metastasis model." (PMID 22807917, 2012). "Nitric oxide regulation of TIMP-1 has been described in cancer cells, as well as macrophages, and fibroblasts, which are key components of tumor stroma." (PMID 22957045, 2012). "The two mechanisms by which TIMP-1 interferes with the metastatic potential of a tumor cell can be demonstrated by the example of the HGF receptor MET." (PMID 22807917, 2012). "Tissue metallopeptidase inhibitor 1 (TIMP1) was found to be significantly (P=0.03) lower expressed in VEGFA165 tumours compared with control tumours." (PMID 22045186, 2011). "TIMP-2 also significantly inhibited tumour cell invasion of Matrigel at 48 h, while inhibition by TIMP-1 was in significant." (PMID 21829200, 2011). "TIFs from MCF7S1 + HMF3s tumours contained slightly lower levels of IL-8 and basic fibroblast growth factor (bFGF) and increased levels of TIMP-1 (cytokine numbers 1, 2, and 3, respectively)." (PMID 20723242, 2010). "EpCAM (p = 0.0001), IL8 (p = 0.0003), MIP-1β (p = 0.0026), MIP-3α (p = 0.039) and TIMP1 (p = 0.0017) levels were significantly different (Mann Whitney U test) between tumours versus AN & PN." (PMID 21092330, 2010). "Correlations between serum CA-125, VEGF-165 and TIMP-1 concentrations and tumor characteristics were calculated by Chi-square tests." (PMID 20388222, 2010). "Overexpression of TIMP-1 has shown to suppress tumorigenesis, in part due to its effects on the tumor vasculature." (PMID 20671917, 2010). "Immunostaining revealed that mice that overexpressed the endogenous TIMP-1 had significantly reduced tumor vessel density compared to controls." (PMID 20671917, 2010). "In this study, we were able to determine the amount of mRNA of MMP-9 and TIMP-1 in the few residual tumour tissues that were available (n=3 for each group, i.e., RGZ-treated (4 weeks) or control mice)." (PMID 20068562, 2010). "EpCAM (p = 0.0001), IL8 (p = 0.0003), CCL4/MIP-1β (p = 0.0026), CCL20/MIP-3α (p = 0.039) and TIMP1 (p = 0.0017) tissue protein levels were significantly different (Mann Whitney U test) between tumours versus AN & PN." (PMID 21092330, 2010). "As mentioned our base model included age, tumor size, malignancy grade, and adjuvant chemotherapy and TIMP-1 was added to this model." (PMID 19744322, 2009). "For mouse assays, we assessed levels of Timp1 and Lcn2 in biological fluids and plasmas from tumor bearing mice (Stage I/II, n = 6; Stage III/IV, n = 5; controls, n = 18)." (PMID 19936259, 2009). "MMP-13 also correlated with the expression of Her-2/neu (p = 0.015) and TIMP-1 (p < 0.010), respectively in tumor cells." (PMID 18373849, 2008). "On the other hand, 12 cases of the present series showed a more intense expression of TIMP-1 in epithelial cells, mainly the mucosal gland, whose structures showed scarce morphological damage, even when the ducts were immersed in tumor cell zones." (PMID 18954439, 2008).
tumor (continued). "Our data suggest that lymph node status, tumor size, Her-2/neu expression, TIMP-1 and MMP-13 expression in cancer cells are independent prognostic factors." (PMID 18373849, 2008). "Platelets physiologically contain MMP-9 and TIMP-1, and the use of serum has therefore been questioned in tumor marker studies." (PMID 19662197, 2007). "In our study celecoxib was able to neutralize the inductive potential of the tumor cell microenvironment by decreasing levels of MMPs, TIMP1, TIMP2, and laminin." (PMID 17156488, 2006). "This paradoxical finding has been suggested to be the consequence of distinct tumour-stimulating functions demonstrated for TIMP-1, for example, stimulation of proliferation and inhibition of apoptosis." (PMID 17047657, 2006). "Since the proteolytic activity of the MMPs is believed to facilitate invasion of cancer cells, one would expect TIMP-1 to inhibit tumour progression." (PMID 17047657, 2006). "TIMP1 in blood plasma correlated not only to tumour stage and grade but also to the lymph node involvement (rs = 0.275; p = 0.027)." (PMID 16901349, 2006). "In HT1080 tumor cells, both protein and mRNA levels of TIMP1, TIMP2, MMP2 and MMP9 are increased by butyrate treatment." (PMID 16972989, 2006). "All MMPs and TIMP-1 were significantly increased in tumour tissue compared to normal gastric mucosa." (PMID 16538217, 2006). "Overexpression of TIMP-1 and TIMP-2 is associated with inhibition of apoptosis and invasive tumour growth." (PMID 16207317, 2005). "Patients with muscle invasive tumours were found to have higher urinary concentrations of TIMP1 than those with superficial tumours." (PMID 15083203, 2004). "In those cancers associated with high levels of TIMP-1 expression, it appears that TIMP-1 drives tumour progression as the result of its ability to stimulate proliferation." (PMID 14735194, 2004). "The ratio of circulating MMP-2/TIMP-1 was also significantly higher in episodes of tumour control vs tumour progression and prior to treatment (P⩽0.0001)." (PMID 12698191, 2003). "Northern blot analysis showed that TIMP-1 mRNA levels correlated directly with tumour aggressiveness: the highest number of TIMP-1 transcripts was found in stages III and IV vs benign goitre (P < 0.0001)." (PMID 10098765, 1999). "Overexpression of TIMP-1 by gene transfer resulted in a significant suppression of the malignant phenotype of NPA cells as judged by an in vitro tumour invasion assay." (PMID 10098765, 1999). "In a multivariate analysis, the T/N ratio of TIMP-1 mRNA was found to be an independent factor influencing the depth of tumour invasion and was the second most important factor in determining the prognosis of patients." (PMID 9275032, 1997). "In liver metastases, MMP-9 localised within peritumour stroma or at the interface between the tumour stroma and normal liver, whereas TIMP-1 mRNA was located throughout the malignant tumour stroma." (PMID 7669564, 1995). "Colony formation analysis demonstrated tumor cell growth to be weakened following TIMP1 knockdown." (PMID 40777024, 2025). "In addition, specific protein abundance of the immunomodulatory proteins TIMP1 and Galectin-1 were lower in VHL-restored tumors compared to VHL-mutated tumor spheroids." (PMID 40736709, 2025). "To further elucidate the spatial relationship between malignant cells and Tregs and investigate whether TIMP1 directly regulates their interaction, we performed multiplex immunofluorescence (mIF) analysis of whole tumor sections." (PMID 41187171, 2025). "In the tumor microenvironment, immune cells contribute to TIMP1 secretion." (PMID 39789100, 2025). "In cancer tissue, TIMP1 is produced by tumor cells, myofibroblasts and various immune cells." (PMID 39789100, 2025). "TIMP1 knockdown markedly attenuated tumor growth in the mice." (PMID 40777024, 2025).
tumor (continued). "TIMP1 regulates the remodelling of the extracellular matrix by inhibiting metalloproteinase activity, which helps tumour cells adapt to changes in the matrix, thereby enhancing cell survival by inhibiting apoptosis, potentially affecting blood vessel formation during MVI." (PMID 39944086, 2025). "Although this correlation was relatively weak, TIMP1 released from necrotic tumor regions may contribute to the activation of circulating immune cells during systemic inflammation." (PMID 39789100, 2025). "This discrepancy may reflect the dual role of TIMP1: it may act as a tumor suppressor by stabilizing the ECM in certain subtypes while promoting immune evasion or resistance in others." (PMID 40565366, 2025). "Therefore, we experimentally verified the infiltration relationship between TIMP1 and treg in tumor tissues." (PMID 41187171, 2025). "On the other hand, a decrease in eigenvector centrality indicates that a gene is connected to less influential or weakening genes, possibly resulting in lower relative influence scores or reduced significance in the network, such as ANXA1, GNB3, POMC, GPER1, and TIMP1 in tumor samples." (PMID 40626556, 2025). "Furthermore, TIMP1 reduction has been shown to alter systemic and microenvironmental metabolism (e.g., lipogenesis and glycolysis), ultimately impairing tumor growth and survival." (PMID 41187171, 2025). "In CRC, TIMP1 correlates with tumor cell proliferation, invasion, and poor prognosis." (PMID 40145096, 2025). "We next asked whether sustained tumor-intrinsic TIMP1 production promotes metastasis from an orthotopic site." (PMID 41511313, 2025). "In addition, tumor-derived TIMP-1 (tissue inhibitor of metalloproteinase-1) triggered NET formation upon interaction with its receptor CD63 and activation of ERK signaling." (PMID 40427186, 2025). "To delve into the mechanism by which TIMP1 regulates Tregs in epithelial cells of the tumor group, we categorized the epithelial cells in the tumor group into TIMP1-positive epithelial cell (TIMP1+Epi) and TIMP1-negative epithelial cell (TIMP1-Epi) subsets based on TIMP1 expression." (PMID 41187171, 2025). "In its MMP-independent tumor-promoting function, TIMP-1 behaves like a cytokine." (PMID 41002380, 2025). "TIMP1 histoscore in tumor cells negatively correlated with T cells located in the CT." (PMID 39789100, 2025). "IL-6, IL-8, monocyte chemoattractant protein-1 (MCP-1), and tissue inhibitor of metalloproteinase-1 (TIMP-1) promote tumor cell growth by activating FAs synthesis, possibly through the involvement of the PI3K/AKT pathway and peroxisome proliferator-activated receptor (PPAR) signaling." (PMID 41421797, 2025). "We evaluated the impact of TIMP1 in a tumor xenograft model." (PMID 40777024, 2025). "Therefore, the high expression of TIMP1 in tumor epithelial cells promotes LGALS9 expression, which interacts with Treg cells through the GALECTIN pathway, thereby enhancing the immunosuppressive function of Tregs." (PMID 41187171, 2025). "Previous studies have highlighted the anti-apoptotic and growth-factor like features of TIMP1 and suggested that its expression in tumor cells may enable cancer to evade immune responses, and create an immunosuppressive microenvironment." (PMID 39789100, 2025). "The xenograft tumor model also indicated that down-regulated TIMP1 markedly blunted tumor growth." (PMID 40687427, 2025). "Notably, TIMP1 maintained consistently higher expression in tumor versus normal epithelial cells throughout pseudotime, with its expression peaking during early-to-mid differentiation phases before declining." (PMID 41187171, 2025). "The increased expression of TIMP1 may facilitate the conversion of macrophages to an immunosuppressive phenotype, thereby promoting tumor cell invasion and immune evasion." (PMID 39859524, 2025). "Importantly, TIMP1 knockdown has been shown to reduce migration, proliferation, and invasion in various tumor cell types." (PMID 40777024, 2025).